LINC02210-CRHR1 (LINC02210-CRHR1 readthrough)
Synonyms: CRHR1-IT1-CRHR1; MGC57346-CRHR1
Gene: Protein-coding gene on chromosome 17 (45,620,344 to 45,835,826, forward strand). Ensembl gene ENSG00000263715.
Genetic constraint (gnomAD): Loss-of-function variants: 17 observed, 33.56 expected, observed/expected ratio (o/e) 0.51, 90% interval 0.35 to 0.76. The upper end of that interval is the gene's LOEUF score, 0.76, which puts it in group 3 of 6, group 1 being the genes least tolerant of losing a copy. Missense variants: 200 observed, 328.1 expected, observed/expected ratio (o/e) 0.61, 90% interval 0.54 to 0.69. Synonymous variants: 101 observed, 125.43 expected, observed/expected ratio (o/e) 0.81, 90% interval 0.68 to 0.95.